CRP (C-reactive protein)
Diseases named in the same sentence as CRP in open-access papers (continued):
Sharing a sentence is not in itself a finding about the gene and the disease.
Sepsis (continued). "After completing a logistic regression analysis, white blood cell (WBC), anemia, procalcitonin (PCT), C-reactive protein (CRP), albumin, and alanine transaminase (ALT) demonstrated a significant difference in differentiating KD from sepsis." (PMID 32792679, 2020). "In this study, we found the Sen, Spe, and DOR of circulating miRNAs for diagnosis of sepsis were higher than PCT and CRP." (PMID 33292630, 2020). "Based on clinical laboratory results, we constructed a novel nomogram model with five laboratory markers (WBC, anemia, CRP, PCT, and ALT) for predicting KD and sepsis, which will help clinicians treat KD and sepsis patients more precisely." (PMID 32792679, 2020). "Despite the routine use of sepsis markers such as complete blood count (CBC) indices, C-reactive protein (CRP), and procalcitonin, there are many confounding factors, false positives, and false negatives which make them less ideal." (PMID 32832553, 2020). "Concentrations of C-reactive protein (CRP) and procalcitonin (PCT) in participants according to clinical relevance of microorganisms detected using REBA Sepsis-ID and blood culture." (PMID 32850901, 2020). "The levels of PCT, CRP and SAA of patients were detected on admission, and the clinical application values of PCT, CRP and SAA for sepsis were compared." (PMID 33235597, 2020). "The main manifestations and laboratory findings of sepsis include fever, elevated white blood cell count (WBC), C-reactive protein (CRP), and procalcitonin (PCT), which are also the manifestations found in KD8." (PMID 32792679, 2020). "The administration of dexmedetomidine significantly improved CRP, PCT, and ALB levels in patients with sepsis requiring mechanical ventilation." (PMID 32778146, 2020). "We found that SIRT1 was associated with ameliorated inflammation and disease severity (reflected by the correlation of SIRT1 with Scr, WBC, CRP, SOFA score, APACHE II score, and albumin) in sepsis patients." (PMID 33263643, 2020). "Many potential sepsis biomarkers have been proposed, procalcitonin (PCT) and C-reactive protein (CRP) being the most frequently studied." (PMID 32503670, 2020). "Patients with sepsis were significantly younger and had significantly higher plasma concentrations of the inflammatory markers PCT, CRP, NGAL and IL‐6 at ICU admission and a significantly longer duration of hospital stay than patients with CAP." (PMID 32916773, 2020). "So, in this study, we were interested in evaluating the CRP, PCT, and IL-6 as sepsis markers for early diagnosis of sepsis in neonates." (PMID 33061986, 2020). "This study summarized the clinicopathological features of the sepsis patients, including body mass index (BMI), white blood cell (WBC), CRP, PCT, APACHE II score, and SOFA score." (PMID 32455124, 2020). "A study investigating DM patients showed that PCT is better than CRP and WBC to anticipating sepsis." (PMID 32399305, 2020). "There wasno significant difference in age (P<0.150), gender (P<0.768), and BMI(P<0.258) between the healthy control group and the sepsis patients group,but significant differences in Scr, WBC, CRP, and PTC were observed(P<0.001)." (PMID 32578720, 2020). "We consider that the great value of CRP in the differential diagnosis of AC with or without sepsis in this study might be associated to the fact that most patients do not seek medical advice in time, with a delay of 2-3 days when they have clinical symptoms like fever." (PMID 32508526, 2020). "So, we recommend platelet count, platelet indices and their ratios, especially plateletcrit and MPV/PCT ratio, should be assessed in all sepsis patients upon admission to the PICU to guide the clinical decision along with the PRISM score and CRP." (PMID 32814554, 2020). "Meanwhile, both presepsin and CRP, as well as the SOFA score, showed significant sepsis prognosis value." (PMID 33374939, 2020).
Sepsis (continued). "Procalcitonin (PCT) and C-reactive protein (CRP) have been the most widely used, but even they have limited ability to distinguish sepsis from other inflammatory conditions or to predict outcomes." (PMID 32284068, 2020). "As a systemic inflammatory response,inflammation-related serum C-reactive protein (CRP), procalcitonin (PTC), andinterleukin (IL-6) have been used in the diagnosis of sepsis, but theirspecificity and sensitivity are limited by different conditions." (PMID 32578720, 2020). "The median concentrations of IL-6, PCT, and CRP were statistically significantly higher in each study subgroup (N-SIRS, SIRS, and sepsis subgroups) compared to the control group." (PMID 32655314, 2020). "The study found that: PCT was superior to hs-CRP and SAA with respect to sensitivity and specificity in the early diagnosis of sepsis." (PMID 33235597, 2020). "In the present study, the use of dexmedetomidine for sedation reduced both CRP and PCT levels in patients with sepsis." (PMID 32778146, 2020). "There are still false positives and false negatives in the diagnosis of AC and sepsis by WBC, CRP, and PCT tests." (PMID 32508526, 2020). "Ten days after the end of chemotherapy, while neutropenic, he developed fever with severe sepsis, and increased procalcitonin (PCT, 40 ng/mL) and C-reactive protein (CRP, 12 mg/dL)." (PMID 33371496, 2020). "A study about postoperative patients with sepsis, LBP plasma concentration showed similar course with CRP in predicting outcome." (PMID 33344378, 2020). "The optimal cut-off values of the 5 days serial measurements of CRP among proven sepsis: CRP1, CRP 2, CRP3, CRP4, and CRP5 were 2.15 mg/L, 8.01 mg/L, 6.80 mg/L, 5.25 mg/L, and 3.72 mg/L, respectively." (PMID 33233806, 2020). "Analytical investigations showed not only that copeptin levels were significantly higher in sepsis cases compared to non-sepsis ones (p < 0.001), but also that they correlated with PCT, CRP, and IL-6 blood levels." (PMID 33092081, 2020). "Concentrations of C-reactive protein (CRP) and procalcitonin (PCT) in participants ≥50 years old according to clinical relevance of microorganisms detected using REBA Sepsis-ID and blood culture." (PMID 32850901, 2020). "In the previous study, sepsis was defined as an abnormal level of WBC, positive C-reactive protein, or positive blood cultures." (PMID 33329342, 2020). "The changes in the levels of PCT, CRP and WBC are established indicators and are widely used inclinical practices that reflect the clinical status and prognosis of sepsis." (PMID 33211058, 2020). "The use of lactate, C-Reactive Protein (CRP), and procalcitonin (PCT) blood tests for the diagnosis and monitoring of patients with suspected sepsis were explored in the survey." (PMID 33114715, 2020). "As expected, inflammatory markers including white blood count (WBC; 14.9 vs. 9.1 g/L, p = 0.011), CRP (213 vs. 12 mg/l, p < 0.0001; normal range <5 mg/l), and PCT (8.8 vs. 0.15 ng/ml, p < 0.0001) were higher in sepsis patients compared to ICU controls." (PMID 33195328, 2020). "Patients with medical admission, sepsis diagnosis at ICU admission, basal CRP > 18.8mg/dL, and score SAPS II > 53 points (Model 3), always (n = 233; 100%) had longer duration of ABD, compatible with the duration of ABD seen in patients with Phenotype C." (PMID 32358385, 2020). "The neutrophil to lymphocyte ratio was calculated to form venous samples taken on admission and compared to the level of CRP, procalcitonin, culture reports, and the SOFA score as a predictor of sepsis." (PMID 33178505, 2020). "His C-reactive protein (CRP) level was 140 mg/L, with blood lactate 2.22 mmol/L, serum procalcitonin (PCT) 32.51 ng/mL, which supported the diagnosis of sepsis." (PMID 31926563, 2020). "Significant differences between the two groups were only observed for CRP and PCT levels (respectively, p < 0.001 and p < 0.016), which were considered reliable post-mortem markers of sepsis." (PMID 33092081, 2020).
Sepsis (continued). "C-reactive protein (CRP) and procalcitonin (PCT) have been widely studied as sepsis biomarkers, but it remains difficult to differentiate sepsis from other non-infectious inflammatory diseases." (PMID 32796893, 2020). "Furthermore, accurate quantification of CRP and IL-6 in sepsis and COVID-19 may be crucial for predicting outcomes, thus potentially enabling early therapeutic interventions and therapy control, e.g., in response to mechanical ventilation or Tocilizumab treatment." (PMID 32912236, 2020). "nCD64%, nCD64 MFI, hs-CRP, PLT, Hb, and ALC achieved significant differences between both sepsis subgroups besides their significant differences between sepsis and control groups." (PMID 33204274, 2020). "The levels of PCT, CRP and SAA have important clinical significance in the diagnosis and treatment of Sepsis and other infectious diseases." (PMID 33235597, 2020). "The plasma markers of inflammation, CRP and IL6, are known to be elevated during inflammation-mediated sepsis and lead to mortality." (PMID 31835381, 2019). "NLR and PLT/MPV performed better as an early sepsis prediction marker in all children compared to WBC, CRP, or PLT count." (PMID 30974881, 2019). "Many clinical studies provide NLR (neutrophil to lymphocyte ratio) in addition to CRP, WBC, and neutrophil count, as an important marker in early bacteremia diagnostics and evaluation of sepsis outcomes." (PMID 30974881, 2019). "And its low expression was associated with advanced disease severity (APACHE II score and SOFA score) and systemic inflammation (CRP, PCT, TNF‐α, IL‐1β, IL‐6, and IL‐17) in sepsis patients." (PMID 31206807, 2019). "CRP and WCC were significantly higher in the sepsis group of those patients who had surgery, when compared with those who did not have surgery." (PMID 31095593, 2019). "Currently, IL-6, CRP and PCT are the most commonly used biomarkers of sepsis, which severity and outcome prediction capacity is of high clinical research interest." (PMID 31781117, 2019). "The serum levels of Scr, WBC, CRP and PCT were higher in sepsis patients than that in healthy controls, whereas the serum albumin level was lower in patients group, and all differences reached significant levels (all P < 0.001)." (PMID 31771650, 2019). "Serial monitoring of serum CRP, PCT, IL-6, IL-1b, sIL-2R, and LBP after death has been suggested to be helpful for the postmortem diagnosis of sepsis, but more studies are needed." (PMID 31661804, 2019). "We compared the NLCR as well as C-reactive protein (CRP) level, procalcitonin (PCT) level, white blood cell (WBC) count, neutrophil count and lymphocyte count on ICU admission between sepsis and non-sepsis ICU patients." (PMID 30811475, 2019). "Plasma concentration of CRP, PCT, and IL-6 decreased after 3 and 5 days of sepsis onset, thus indicating a gradual resolution of systemic inflammation." (PMID 31221993, 2019). "Compared to the discovery set, mean differences between SIRS and sepsis patients for SOFA scores were around 3.5 points lower and for CRP concentrations around 120 mg/mL higher." (PMID 31075840, 2019). "Biomarkers, such as procalcitonin (PCT), C-reactive protein (CRP), and presepsin, can aid in the diagnosis/exclusion of sepsis." (PMID 31226876, 2019). "Currently, white blood cell (WBC) count, C-reactive protein (CRP) and procalcitonin (PCT) are commonly used to detect sepsis." (PMID 30811475, 2019). "Compared to ICU controls, community-acquired severe sepsis patients had higher levels of PCT (p = 0.008), hs-CRP (p = 0.020), lower Th1 population (p = 0.004) and higher T helper 2 cells (p < 0.001) along with higher Th2/Th1 (p < 0.001) at admission." (PMID 30813927, 2019). "In recent years, research groups have demonstrated POC sensors for the detection of sepsis by monitoring PCT and CRP levels." (PMID 33117982, 2019). "C-reactive protein (CRP) and procalcitonin (PCT) have been widely used to facilitate the diagnosis of sepsis, but the clinical values of these are limited." (PMID 31243609, 2019).
Sepsis (continued). "Several proteins identified in this study, including Transthyretin (TTR) and C-reactive protein (CRP), have already been used to diagnose sepsis clinically." (PMID 31568522, 2019). "First, patients with sepsis exhibited significantly higher serum WBC counts, as well as AGP and CRP levels, and lower Hb and platelet levels than healthy volunteers." (PMID 31309103, 2019). "Our results indicate that AGP is a more valuable prognostic predictor during sepsis than other widely used indicators and severity scores, such as WBC counts, APACHE-II scores, and CRP, lactate, and procalcitonin levels." (PMID 31309103, 2019). "C-reactive protein (CRP) is a more useful tool in predicting improvement and outcome in patients admitted with sepsis when compared to scoring systems like SOFA score." (PMID 31065202, 2019). "More than 170 biomarkers have been identified for the assessment of sepsis, including PCT, CRP, TNF-α/IL-6, MCP-1, miRNA, and other indicators." (PMID 31671729, 2019). "Among the laboratory biomarkers, CRP level, WBC count, PLT/MPV, and NLR were the best discriminators between sepsis/bacteremia patients and those with viral infection." (PMID 30974881, 2019). "For both NK cells and granulocytes, the mean sequential organ failure assessment (SOFA) score was by almost 8 points higher in sepsis than in SIRS, and the C-reactive protein (CRP) mean concentration in blood plasma was about 3-fold higher." (PMID 31075840, 2019). "The levels of copeptin were found to be significantly higher in sepsis cases, and the concentrations correlated with PCT, CRP, and IL-6 values." (PMID 31661804, 2019). "Mechanical ventilation, white blood cell (WBC) counts, C-reactive protein (CRP) and lactate levels, maximum 24-h APACHE-II scores, and AGP concentrations were significantly higher upon admission in patients with sepsis who died." (PMID 31309103, 2019). "The median CRP values (IQR) in the control, sepsis, and septic shock groups were 3.6 (2.0–5.2), 9.9 (4.9–20.2), and 10.5 (7.3–21.0) mg/dL, respectively." (PMID 31718563, 2019). "C-reactive protein (CRP), as a marker of generalized inflammation, was only measured in patients with sepsis." (PMID 31581250, 2019). "Using circulating biomarkers, such as C-reactive protein (CRP) and procalcitonin (PCT), to accurately diagnose, manage and treat infection-induced inflammatory diseases, like sepsis and pneumonia, is a highly researched medical field." (PMID 31419260, 2019). "Although the plasma C-reactive protein level was increased in the CKD and sepsis groups, the increase was significant only in the sepsis group (p = 0.068 vs. p = 0.024)." (PMID 31795376, 2019). "For patients with sepsis and septic shock, NLR and CRP values on admission to the ICU (within the first 24 h) are not as valuable as the 1st day SOFA and APACHE II scores for predicting mortality." (PMID 31648506, 2019). "Infection-related laboratory markers (C-reactive protein, white blood cell count) were equally, substantially elevated in both groups (average CRP concentration well-above 100 mg/L, and WBC above 12 G/L), with at least half (54–60%) of subjects with sepsis." (PMID 30949171, 2019). "The NLCR is less suitable than conventional inflammatory markers CRP and PCT to detect the presence of sepsis in ICU patients." (PMID 30811475, 2019). "CRP 2 cut-off levels of LONS group and proven sepsis group were found to be lower than the initial values." (PMID 30068303, 2018). "A/GSN ratios positively correlated with CRP levels and sequential organ failure assessment (SOFA) clinical scores, supporting its potential as a novel prognostic marker for sepsis." (PMID 30149613, 2018). "As a predictor of the persistence/development of severe sepsis on the third day of observation (n = 46), the highest AUC was shown for PCT, followed by sTREM-1, IL-6 and CRP." (PMID 29282483, 2018). "We found significant cut-offs of CRP 2 levels to be lower than the initial values in LONS and proven sepsis groups." (PMID 30068303, 2018).
Sepsis (continued). "The significant CRP 2 cut-off levels of LONS group and proven sepsis group were found to be lower than the initial values." (PMID 30068303, 2018). "In all patients with sepsis, serum tenascin-C was significantly positively correlated with SOFA score (P = 0.011), serum creatinine (P = 0.006), CRP (P = 0.001), IL-6 (P < 0.001) and TNF-α (P = 0.026)." (PMID 30442110, 2018). "The study included patients treated in a neurological intensive care unit and serum levels of C-reactive protein and S–PCT were evaluated on admission day, on the day of diagnosis of SIRS or sepsis, and on days three and seven after the diagnosis." (PMID 29891780, 2018). "Second to CRP, PCT to date has become the most widely utilized biomarker in sepsis management worldwide." (PMID 30087610, 2018). "Also, infants with a diagnosis of ventilator-associated pneumonia and elevated CRP were not considered as having a late-onset sepsis since the objective of the study was to assess diagnostic accuracy in predicting culture-proven bloodstream infections or meningitis." (PMID 29382319, 2018). "Several serum biomarkers, including lactate, C-reactive protein (CRP), and procalcitonin (PCT), are used to guide management in sepsis and are an important part of early goal directed therapy." (PMID 30280095, 2018). "At the time of suspicion of sepsis, in each sepsis subgroup, other than EONS, the comparison of ROC curves of CRP and MPV and the comparison of ROC curves of PCT and MPV (p < 0.001) were found to be statistically significant." (PMID 30068303, 2018). "In summary, this study is the first that describes the combined CRP and CBC for the diagnosis of late-onset sepsis in a large cohort of VLBW neonates." (PMID 29382319, 2018). "Even CRP and PCT therapeutic values have been challenged due to difficulties in distinguishing sepsis from other inflammatory diseases." (PMID 30149613, 2018). "It should be noted that the importance of PCT and CRP remain unchanged and ever, NLR and MPV values should alert clinicians to the possibility of sepsis and to initiate or change antibiotic treatment." (PMID 30190753, 2018). "GH therapy reduces the levels of CRP in GHD patients, and exerts anti-inflammatory effects in different experimental models of sepsis by lowering TNF-α." (PMID 29346331, 2018). "sTREM-1 was able to predict the development of severe sepsis, however, PCT was superior to sTREM-1, CRP and IL-6 in predicting severe sepsis and septic shock on the third day of treatment." (PMID 29282483, 2018). "The median PCT 1 (p < 0.001) and PCT 2 measurements (p < 0.001), the CRP 1 level (p < 0.001), and the MPV 2 (p < 0.001) measurement were significantly higher in the proven sepsis group than the neonates with clinical sepsis." (PMID 30068303, 2018). "We found that the traditional biomarkers of WBC, CRP and PCT in the study of 43 cases of neonatal infection showed significant differences between the sepsis group and normal control group." (PMID 29968788, 2018). "Although no significantly difference was found between the performances of CRP and PCT measurement in sepsis subgroups, we found that PCT and CRP had higher performances than MPV for the first 24 h of diagnosis of preterm neonatal sepsis." (PMID 30068303, 2018). "CRP level and MPV value were significantly higher in the sepsis group compared with the non-sepsis group (p=0.006, p= 0.001 respectively)." (PMID 30190753, 2018). "We determined that the PCT and CRP levels and the MPV measurements are significantly higher in the preterm patients with sepsis." (PMID 30068303, 2018). "A study of adults with suspected bacteremia and sepsis, which grouped the patients according to PCT levels, determined correlations between PCT and WBC, CRP and NLR." (PMID 30190753, 2018).